CCHCR1 (coiled-coil alpha-helical rod protein 1)
Description:
May be a regulator of keratinocyte proliferation or differentiation.
Synonyms: Pg8; C6orf18; HCR; SBP
Tractability: PROTAC: ubiquitination databases record sites on it.
Safety:
Unwanted effects reported when the protein is acted on. In parentheses: how it was acted on, where the effect was seen, and who reports it.
Nevirapine-induced rash (source: ClinPGx)
rash (source: ClinPGx)
Gene: Protein-coding gene on chromosome 6 (31,142,439 to 31,158,238, reverse strand). Ensembl gene ENSG00000204536.
Subcellular location: Cytoplasm; Nucleus
Subcellular location (Human Protein Atlas): Cytosol
Gene Ontology:
Molecular function: protein binding
Biological process: protein export from nucleus; cell differentiation
Cellular component: centriole; cytosol; cytoplasm; nucleus
Genetic constraint (gnomAD): Loss-of-function variants: 89 observed, 111.32 expected, observed/expected ratio (o/e) 0.8, 90% interval 0.67 to 0.95. The upper end of that interval is the gene's LOEUF score, 0.95, which puts it in group 4 of 6, group 1 being the genes least tolerant of losing a copy. Missense variants: 894 observed, 1,093.5 expected, observed/expected ratio (o/e) 0.82, 90% interval 0.77 to 0.86. Synonymous variants: 375 observed, 438.34 expected, observed/expected ratio (o/e) 0.86, 90% interval 0.79 to 0.93.
Homologues: Orthologues: macaque CCHCR1 (96% identical), chimpanzee CCHCR1 (96% identical), dog CCHCR1 (81% identical), pig CCHCR1 (79% identical), rat Cchcr1 (72% identical), mouse Cchcr1 (72% identical), guinea pig CCHCR1 (68% identical), tropical clawed frog cchcr1 (30% identical), zebrafish si:dkeyp-20g2.1 (21% identical), Caenorhabditis elegans B0432.7 (9% identical), zebrafish si:dkeyp-20g2.1 (6% identical). Paralogues in human: CCDC57 (15% identical), CIP2A (13% identical).
Diseases named in the same sentence as CCHCR1 in open-access papers:
CCHCR1 is named in the same sentence as 44 diseases in open-access papers, as found by Europe PMC text mining. Sharing a sentence is not in itself a finding about the gene and the disease. The quoted sentences say what the papers report.
psoriasis (27 papers, 2009 to 2025). An autoimmune condition characterized by red, well-delineated plaques with silvery scales that are usually on the extensor surfaces and scalp. "The protein CCHCR1, which is located in prominent psoriasis susceptibility region PSORS1, is a strong candidate gene linked to the psoriasis risk allele CCHCR1* HLA-Cw6." (PMID 40756258, 2025). "The coiled-coil alpha-helical rod protein 1 (CCHCR1) was first identified as a candidate gene in psoriasis and has lately been found to be associated with a wide range of clinical conditions including COVID-19." (PMID 38128007, 2023). "The gene encoding CCHCR1 maps to a genetic locus that is associated with an increased risk of psoriasis." (PMID 36877681, 2023). "The gene encoding coiled-coil alpha-helical rod protein 1 (CCHCR1) is in a genomic locus that is associated with the development of psoriasis." (PMID 36877681, 2023). "Ours is the first study to identify an association between FCGR2A, TNFR1, CD226, TNFAIP3, and CCHCR1 and age at onset of psoriasis." (PMID 26613086, 2015). "Current evidence indicates that CCHCR1 is associated with Psoriasis, a disease with hyperproliferative lesions of the skin." (PMID 24664238, 2014). "In contrast to benign KC hyperproliferation in psoriasis, the hyperproliferation marker Ki67 expresion in vivo and in vitro was associated with CCHCR1 expression in malignant transformation." (PMID 22218424, 2012). "The isoform 1 with the non-risk allele induces the expression of keratin 17, a hallmark for psoriasis; the silencing of CCHCR1 reduces its expression in HEK293 cells." (PMID 23189171, 2012). "CCHCR1 (Coiled-Coil α-Helical Rod protein 1), within the major psoriasis susceptibility locus PSORS1, is a plausible candidate gene with the psoriasis associated risk allele CCHCR1*WWCC." (PMID 23189171, 2012). "Keratin 17 (KRT17) is implicated in the psoriasis pathogenesis and its expression is altered in experiments with transgenic mice overexpressing CCHCR1." (PMID 23189171, 2012). "The role of CCHCR1 as a susceptibility gene for psoriasis was strengthened by genome-wide association studies where the SNPs (rs130065, rs130076, rs3130453) from the coding region of CCHCR1 showed strong association to psoriasis with P-values varying between 10−4 and 10−150." (PMID 23189171, 2012). "Even though CCHCR1 resides in the chromosomal region showing the strongest associations in genome-wide association studies, its role and function in the pathogenesis of psoriasis is still unclear." (PMID 23189171, 2012). "Here we studied if either of the alleles Iso1 or Iso3 associates with psoriasis in family samples and whether the extended N-terminus of isoform 1 affects the localization and function of CCHCR1." (PMID 23189171, 2012). "Interestingly, we also demonstrated that CCHCR1 co-localizes at the centrosome with β-catenin, a protein implicated in psoriasis." (PMID 23189171, 2012). "SNP rs1265181 in HCG27 is the top association signals in a GWAS of psoriasis in Han Chinese population, while rs130065 in CCHCR1 has been consistently associated with psoriasis in multiple populations, and HCR1 protein expressed differently between lesional skin and normal skin." (PMID 22125590, 2011). "Thus, in contrast to benign KC hyperproliferation in psoriasis, Ki67 expression in vivo and in vitro associated with CCHCR1 expression in malignant transformation." (PMID 19551138, 2009). "Furthermore, our mouse model overexpressing the CCHCR1*WWCC psoriasis risk allele under keratin 14 promoter shows impaired proliferation capability of KCs, suggesting less active activator protein 1 (AP-1) mediated signaling in the risk mice." (PMID 19551138, 2009). "Therefore it was suggested that it could be involved in psoriasis susceptibility, but the connection of changes in the CCHCR1 gene with psoriasis is still the subject of investigations." (PMID 22218424, 2012).
psoriasis (continued). "These discoveries shed light on the intricate role of CCHCR1 in psoriasis development, underscoring the need for further investigations of its potential as a therapeutic target." (PMID 40756258, 2025). "The function of CCHCR1 remains little comprehended, whereas CDSN encodes a keratinocyte protein implicated in skin desquamation, a process recognized to be disrupted in psoriasis." (PMID 40690118, 2025). "The function of CCHCR1 isoforms in psoriasis together with the IL-17-dependent mechanisms regulating their expression pattern in psoriatic skin remains to be elucidated." (PMID 38495872, 2024). "CCHCR1 (coiled-coil alpha-helical rod protein 1) is a candidate gene for psoriasis, a skin condition affecting 1% to 2% of the population." (PMID 38128007, 2023). "The CCHCR1 gene, well known as a candidate gene for psoriasis, has received ample attention in clinical research in the last decade." (PMID 38128007, 2023). "The function of CCHCR1 isoforms in psoriasis together with the IFN-γ and IL-17-dependent mechanisms regulating their expression pattern in psoriatic skin remains to be elucidated." (PMID 36423071, 2022). "The coiled-coil alpha-helical rod protein 1 (CCHCR1, also known as HCR) gene is considered to be a psoriasis susceptibility gene, and the protein is suggested to be localized to the P-bodies and centrosomes in mammalian cells." (PMID 36280838, 2022). "Our study supported the involvement of CCHCR1 in AA pathogenesis, but further experiments will be needed to prove the involvement of CCHCR1 in psoriasis." (PMID 34356904, 2021). "CCHCR1 (Coiled-Coil α-Helical Rod protein 1) is a putative PSORS1 candidate gene among others, and its CCHCR1*WWCC allele is associated with psoriasis in several populations." (PMID 29866042, 2018). "Several studies have previously proved the association between candidate genes involved in metabolic pathways of acitretin and the pathogenic mechanism of psoriasis, such as CSMD1, CCHCR1, GLI1, SFRP4 etc.." (PMID 28146080, 2017). "Of these, three (HLA-C, CCHCR1 and CDSN) were highly polymorphic and harbored coding variants that were significantly associated with psoriasis." (PMID 29186830, 2017). "While the function of CCHCR1 is still poorly understood, CDSN encodes a keratinocyte protein involved in skin desquamation, a process that is known to be altered in psoriasis." (PMID 29186830, 2017). "Comparison between patients with type I psoriasis and patients with type II psoriasis revealed significant associations for the following genes: FCGR2A, TNFR1, CD226, PSORS6, TNFAIP3, HLA-C, TNF-α, and CCHCR1." (PMID 26613086, 2015). "The CCHCR1 protein has been suggested to have a role in the pathogenesis of psoriasis potentially by interfering with keratinocyte differentiation." (PMID 24664238, 2014). "The CCHCR1 gene (also known as HCR, Pg8, SBP or C6orf18) is highly polymorphic and has been shown to be located within the major psoriasis susceptibility locus." (PMID 24664238, 2014). "The CCHCR1 gene is highly polymorphic and has the allele CCHCR1*WWCC associated with psoriasis in several populations." (PMID 23189171, 2012). "The centrosomal localization of CCHCR1 provides a connection to the abnormal cell proliferation and offers a link to possible cellular pathways altered in psoriasis." (PMID 23189171, 2012). "To study the possible connection between the CCHCR1 isoforms and psoriasis, we genotyped the SNP rs3130453 (G/A) in 508 Finnish and Swedish psoriasis families." (PMID 23189171, 2012). "The most important chromosomal region for psoriasis predisposition is PSORS1 in the Human Leukocyte Antigen region (HLA, 6p21.3) where also CCHCR1 (Coiled-Coil α-Helical Rod protein 1), by position a plausible psoriasis candidate gene, is located." (PMID 23189171, 2012).
psoriasis (continued). "The locus associated with total WBC count on chromosome 6p21 contains genes associated with follicular lymphoma (CHCG22), progression of HIV-1 infection (CDSN, PSORS1C1 and PSORS1C2) and psoriasis (CCHCR1, PSORS1C1 and PSORS1C2)." (PMID 21738480, 2011). "Distinct from the benign hyperproliferative disorder psoriasis, expression of the hyperproliferation marker Ki67 was demonstrated here in the same areas as CCHCR1 expression at the invasive front of SCCs." (PMID 19551138, 2009). "The present study implicates that CCHCR1, a candidate gene for psoriasis, has a function in KC biology also in malignant transformation." (PMID 19551138, 2009). "Staining for the cell proliferation marker Ki67 shows inverse correlation to CCHCR1 in psoriasis lesions, consistent with a role in KC proliferation." (PMID 19551138, 2009). "CCHCR1 is involved in the pathogenesis of psoriasis, skin cancer and alopecia areata." (PMID 40730494, 2025). "The results, however, should not be over interpreted, as psoriasis is a complex disease and CCHCR1 is a susceptibility gene among several others, and as mentioned the direct comparison of CCHCR1 cells and skin samples is not warranted." (PMID 29866042, 2018). "CCHCR1 is expressed in psoriatic skin in counterpart to normal skin; transgenic mice with two variants of CCHCR1 do not express a psoriasis picture but present abnormal keratinocyte proliferation suggesting a potential role for this gene in this process." (PMID 25973436, 2015). "Here we present that CCHCR1 localizes at the centrosome and via affecting cytoskeletal organization and cell proliferation, has haplotype specific functional consequences relevant to the pathogenesis of psoriasis." (PMID 23189171, 2012). "Our results presented here show that CCHCR1, a candidate gene for psoriasis, was expressed in the majority of SCCs, BCCs and KAs studied, suggesting that CCHCR1 may have a role not only in KC proliferation but also in transformation." (PMID 19551138, 2009). "Different from psoriasis, Ki67 had a similar expression pattern as CCHCR1." (PMID 19551138, 2009). "We conclude that both in psoriasis and the early stages of KC transformation, CCHCR1 may function as a negative regulator of proliferation, but beyond a certain point in oncogenesis cannot control this phenomenon any longer." (PMID 19551138, 2009). "In psoriasis, CCHCR1 expression was most intense in areas with less Ki67 positive KCs." (PMID 19551138, 2009). "The localization of CCHCR1 to the centrosome establishes a possible connection to aberrant cell proliferation and offers insight into the cellular pathways that may be altered in psoriasis." (PMID 40756258, 2025). "Coiled-Coil alpha-helical Rod protein 1 (CCHCR1) is a component of P bodies, and in the PSORS1 locus, a risk locus for psoriasis, could modulate the localisation and function of P bodies in patient keratinocytes that were positive for the SNPs associated with PSORS1." (PMID 33291764, 2020). "Furthermore, our results suggest that CCHCR1 might function in EGFR-STAT3 signaling, previously implicated in psoriasis as well." (PMID 23189171, 2012). "We have previously shown that the CCHCR1 gene within the major psoriasis susceptibility locus PSORS1 may function as a negative regulator of KC proliferation." (PMID 19551138, 2009). "CCHCR1 is located 110 kb away from the HLA-C locus and is positioned between the CDSN and SC1 genes, and it has also been thought to be involved in the pathogenesis of psoriasis in a transgenic mouse model." (PMID 34356904, 2021). "In these tumors, unlike in psoriasis, CCHCR1 is expressed especially in proliferating cells (Ki67 positive)." (PMID 23189171, 2012). "Aberrant function of the CCHCR1 gene (Coiled-Coil α-Helical Rod protein 1, HCR) within the PSORS1 locus may contribute to the onset of psoriasis." (PMID 19551138, 2009).
psoriasis (continued). "As psoriasis and cancer share some characteristics, such as accelerated cell proliferation, angiogenesis, and inflammation, we have previously studied the expression of CCHCR1 in the non-melanoma skin cancers squamous cell carcinoma (SCC) and basal cell carcinoma (BCC)." (PMID 23189171, 2012). "Previously, we could not observe correlation with CCHCR1 and Ki67 in psoriasis lesions nor in PMA-induced hyperproliferation of transgenic mouse skin, and analogously in the current study, we found negative correlation in the proliferation assay of benign HaCaT cells." (PMID 19551138, 2009).
COVID-19 (6 papers, 2022 to 2025). A disease caused by infection with severe acute respiratory syndrome coronavirus 2. "Moreover, we identified several shared genes, such as HLA-B and CCHCR1, previously implicated in either COVID-19 or PrCa, which support the robustness of our findings and point to potential targets for diagnosis and therapy." (PMID 41210689, 2025). "Notably, the CCHCR1 gene has recently been linked to alopecia areata, type-2 diabetes, Takayasu arteritis, and COVID-19 susceptibility, emphasizing the importance of understanding its cellular function and transcription regulation." (PMID 38128007, 2023). "Among them, CCHCR1 was shared by PrCa with all three COVID-19 phenotypes, highlighting its significance in our study." (PMID 41210689, 2025). "Among them, HLA-C, TCF19, and ADAM15 were shared by PrCa and the two COVID-19 severity phenotypes, while CCHCR1 was shared by PrCa and all three COVID-19 phenotypes." (PMID 41210689, 2025). "Although the specific role of CCHCR1 between COVID-19 and PrCa has not been reported, this evidence suggests possible mechanisms involving the combination of immunosuppression and androgens." (PMID 41210689, 2025).
alopecia areata (4 papers, 2021 to 2025). Loss of scalp and body hair involving microscopically inflammatory patchy areas. "We recently discovered a nonsynonymous variant in the coiled-coil alpha-helical rod protein 1 (CCHCR1) gene within the alopecia areata (AA) risk haplotype." (PMID 34356904, 2021).
skin cancer (3 papers, 2009 to 2025). "CCHCR1 is up-regulated in skin cancer and associated with EGFR expression." (PMID 31332212, 2019). "To further understand the function of CCHCR1 in KC transformation and skin cancer, we studied its expression in premalignant and malignant squamous lesions and basal cell carcinoma (BCC)." (PMID 19551138, 2009). "The positive correlation with CCHCR1 and Ki67 expression in skin cancers was supported by the expression profiling of cutaneous SCC cell lines." (PMID 19551138, 2009). "To study the role of CCHCR1 in KC proliferation and transformation, we investigated CCHCR1 protein expression by immunohistochemistry in different skin tumors in relation to EGFR, its downstream target cyclin-D1, and the hyperproliferation marker Ki67." (PMID 19551138, 2009). "As CCHCR1 is expressed in certain cancers and regulates keratinocyte (KC) proliferation in a transgenic mouse model, we studied its relation to proliferation in cutaneous squamous cell cancer (SCC) cell lines by expression arrays and quantitative RT-PCR and in skin tumors by immunohistochemistry." (PMID 19551138, 2009).
cervical cancer (2 papers, 2012 to 2014). A primary or metastatic malignant neoplasm involving the cervix. "Santin and colleagues identified CCHCR1 (herein named C6orf18) among many other genes overexpressed in primary cervical cancer cultures when compared to normal cervical keratinocytes." (PMID 24664238, 2014). "In line with this hypothesis, several links between CCHCR1 and HPV-associated cervical cancer were detected." (PMID 24664238, 2014). "Overexpression of the CCHCR1 gene could stimulate the proliferation of cervical carcinoma cells at the early stages of neoplasia." (PMID 22218424, 2012). "Interestingly, CCHCR1 gene expression was slightly decreased in cervical carcinoma cells, compared with control probes." (PMID 22218424, 2012). "We show that E2 binding to CCHCR1 is specific of the HPV16 genotype, the most prevalent HPV in cervical cancer." (PMID 24664238, 2014). "The highest CCHCR1 mRNA levels were observed in H-SIL probes, whereas the levels were lower in cervical carcinoma compared to control probes." (PMID 22218424, 2012). "In the present study, the CCHCR1 gene coding sequence and its expression was analyzed in normal, precancerous and cervical cancer cells." (PMID 22218424, 2012). "The level of CCHCR1 transcripts was determined using the real-time PCR method and the highest gene expression was detected in the H-SIL group and slightly decreased in the cervical carcinoma cells, compared with the control probes." (PMID 22218424, 2012).
actinic keratosis (1 paper, 2009). A precancerous lesion of the skin composed of atypical keratinocytes. "Eight of 11 studied actinic keratosis (AK) specimens had CCHCR1 positive basal or suprabasal KCs." (PMID 19551138, 2009).
alcohol dependence (1 paper, 2025). Physical and psychological dependence on alcohol. "CCHCR1 has not been explored in alcohol dependence but may serve as a prospective drug target in the future." (PMID 40730494, 2025).
alcohol use disorders (1 paper, 2025). "Whole‐exome sequencing of 83 alcohol use disorder patients identified 106,525 SNVs and 19,826 InDels, revealing six genes (CNTNAP3, ZNF683, ALDH2, CCHCR1, ZNF45, ESRRA) with deleterious mutations through comprehensive bioinformatics analysis." (PMID 40730494, 2025).
basal cell carcinoma (1 paper, 2009). A carcinoma involving the basal cells. "CCHCR1 protein was detected in the pushing border of SCC and lining basal cell carcinoma islands." (PMID 19551138, 2009).
Bowen's disease (1 paper, 2009). "Spongiosis, inflammatory infiltrate, and capillary proliferation were associated with CCHCR1 expression in 11/21 Bowen's disease (SCC in situ) samples." (PMID 19551138, 2009). "In Bowen's disease, cytoplasmic CCHCR1 staining was encountered basally and suprabasally in dermal papillae resembling CCHCR1 staining of psoriatic lesional skin, especially in hypertrophic samples." (PMID 19551138, 2009). "Also EGFR expression in Bowen's disease resembled the expression pattern of CCHCR1." (PMID 19551138, 2009).